SFN (stratifin)
Diseases named in the same sentence as SFN in open-access papers (continued):
Sharing a sentence is not in itself a finding about the gene and the disease.
tumor (continued). "Moreover, our results indicate that SFN plays important roles in HCC proliferation, migration, invasion, and tumor growth and induces EMT by activating Wnt/β-catenin signaling." (PMID 37587914, 2023). "The investigation of clinicopathological parameters showed that SFN was highly expressed in tumor size of <5 cm and in nonmenopausal ages, while CCDC18-AS1 and LINC01343 indicated a high expression in stages II-III and III of BC, respectively." (PMID 36160032, 2022). "Our findings are that the expression of SFN gene was significantly higher in the BC tissues with tumor size less than 5 cm and also in nonmenopause ages compared to the normal group (p=0.0207 and p=0.0145, respectively)." (PMID 36160032, 2022). "The genetic interaction between Kdf1 and more widely studied stratifin proves that KDF1 may be related to tumor progression." (PMID 35281796, 2022). "Among them, SFN was found to be upregulated in both GSE14814 and GSE42127 datasets and was also found to significantly upregulate in recurrent NSCLC patient tissue when compared in para-tumor normal tissue and primary cancer tissue." (PMID 34553022, 2021). "We found that differential methylation of the ITGA4, SFN, ITGA2, PIK3CD, and PIK3R1 genes allowed the discrimination between normal and tumour tissue evidencing that all 12 CpGs identified were good to excellent diagnostic biomarkers with AUC > 0.8 in two independent cohorts." (PMID 34944974, 2021). "The results showed that the expression of SFN was significantly higher in tumor tissues than normal tissues, as well as in CC cells than normal cell." (PMID 31779593, 2019). "Based on the key roles of CENPA and SFN in LIHC progression, future studies can further explore the molecular regulatory network of these two genes in LIHC pathogenesis, study their functions in the tumor microenvironment, and evaluate their application value in personalized treatment." (PMID 40251374, 2025). "Interestingly, from this independent cohort of PDAC (178 patients), we observed that SFN expression from bulk tumours (i.e. without LCM of the stroma) was predictive of patient survival." (PMID 32376891, 2020). "Notably, enforced stratifin (14‐3‐3σ; SFN) overexpression could increase pT606‐Kaiso accumulation in the cytoplasm and de‐repress the transcription of Kaiso target gene cadherin 1 (CDH1), which is a tumour suppressor." (PMID 35851744, 2022). "Similarly, when sFn was pre-treated with P4 and incubated with monocytes, and tumor cells were incubated with sFn, no inhibition was observed, because the free α Mβ2 could still bind to sFn on the tumor cells (Bar 7; +/+P4)." (PMID 16925817, 2006). "Similarly, Sfn (Stratifin, also known as 14-3-3 protein sigma) was also increased in 4NQO-induced tumors, matching results from prior studies, which showed Sfn to be over-expressed in human HNSCC tumor samples in relation to non-cancerous head and neck tissues." (PMID 36672394, 2023).
cancer (83 papers, 2006 to 2025). A tumor composed of atypical neoplastic, often pleomorphic cells that invade other tissues. "SFN has a role in suppressing cancer cell growth and metastasis and has been implicated in regulating a range of proteins involved in oncogenesis." (PMID 40004538, 2025). "SFN is frequently silenced by hypermethylation in human cancers, and its decreased expression has been associated with the metastasis of several human cancers." (PMID 30566430, 2018). "SFN, as well as other naturally occurring isothiocyanates, can also block cancer development by causing cell cycle arrest and apoptosis induction in cancer cells." (PMID 25821782, 2015). "CDH1 and SFN are important tumor suppressor genes whose loss of function has been implicated in many types of cancers." (PMID 25286960, 2014). "Stratifin, SFN (14-3-3 sigma), plays a role in various cellular processes being the most cancer-associated 14-3-3 isoform." (PMID 22673103, 2012). "Among the different genes in this family, the 14-3-3sigma (SFN) isoform has been mostly implicated in human cancer." (PMID 19936097, 2007). "Specifically, pathway analysis revealed that miR‐7704, can inhibit targets, including TSC1/2, which is a negative regulator of mTOR1 to promote cell growth, and SFN or stratifin factor, which is associated with cancer treatment resistance and PI3K/AKT signaling." (PMID 38819439, 2024). "However, the overexpression of SFN was also reported to be associated with a better prognosis, lower early cancer recurrence rates, and distant metastasis following resection." (PMID 36300097, 2022). "CpG island methylation and loss of SFN expression have been detected in different types of cancer." (PMID 19936097, 2007). "The SFN gene (14-3-3σ proteins or stratifin) is one of various genes implicated in several cancer pathways, as it plays multifunctional regulatory role in several cellular processes related to cancer pathophysiology, including cell cycle progression, cell growth, and apoptosis." (PMID 36160032, 2022). "Additionally, up-regulation of SFN expression is associated with age and cancer grades." (PMID 30926680, 2019). "We found that EPCAM is significantly upregulated in CNV cancer cells, while SFN expression is downregulated." (PMID 40244296, 2025). "The results revealed that EPCAM was highly expressed in CNV cancer cells, while SFN was expressed at low levels." (PMID 40244296, 2025). "Previous studies have suggested that SFN is involved in various types of tumors, including lung, renal, liver, and breast cancer." (PMID 40722651, 2025). "14-3-3σ (stratifin, SFN) is a member of 14-3-3 proteins family in humans that promote cancer progression." (PMID 38843383, 2024). "Some of these genes are biomarkers for squamous metaplasia, SFN genes help in cell death in cancer cells via apoptosis." (PMID 39140365, 2024). "Upon DNA damage, SFN binds to Akt protein, leading to G2/M cell cycle arrest and consequently affecting cancer cell proliferation and apoptosis." (PMID 37946061, 2024). "During the process of cancer cell morphological transformation, the interaction between SFN and LIMK2-cofilin signaling pathway plays a role by influencing cellular cytoskeletal remodeling." (PMID 37946061, 2024). "We observed the expression level of SFN in pan-cancer and found that SFN were highly expressed in 12 cancer types." (PMID 38297333, 2024). "Previous studies have demonstrated that SFN is an oncogene, accelerating tumorigenesis and progression across various cancer types." (PMID 37398672, 2023). "COL17A1, KRT15, KRT17, S100A2, SFN, which have been shown to assume oncogenic roles in various cancers, were among the highly changed genes and positively correlated with p63 expression." (PMID 38012140, 2023). "The expression of the SFN gene varies in different cancers, and it performs a double-edged function." (PMID 35547358, 2022). "SFN gene expression in cancer tissues was significantly increased (p=0.0001) in comparison to control tissues." (PMID 36160032, 2022).
cancer (continued). "In the pancancer view based from the ULCAN tool, we found that SFN was upregulated in 16 cancer types, downregulated in 6 cancer types, and equally expressed in 2 cancer types." (PMID 35547358, 2022). "Upregulated SFN gene expression in PC and other cancer types was observed in ONCOMINE, UALCAN, and GENT2." (PMID 35547358, 2022). "Conversely, upregulation of the SFN gene expression has been observed in other cancers, including pancreatic, colorectal, and esophageal squamous cell carcinoma." (PMID 35547358, 2022). "Decreased SFN expression has been found in various cancers, including breast, lung, liver, endometrium, head and neck, vulva, and prostate cancers." (PMID 35547358, 2022). "We analyzed the expression pattern of SFN in numerous cancer studies by using the ONCOMINE platform." (PMID 35547358, 2022). "The clinicopathological analysis using the ULCAN tool showed that the intensity of SFN expression is commensurate with cancer progression." (PMID 35547358, 2022). "SFN is an anti-cancer substance found in broccoli, which inhibits cell growth and induces apoptosis in various cancer cells." (PMID 36358786, 2022). "SFN is one of the members of the 14-3-3 family, which is known as human mammary epithelial cell marker (HME-1) and has been directly associated with cancer." (PMID 36160032, 2022). "SFN, strongly expressed in many cancers, is involved in carcinogenesis through the regulation of cell proliferation, differentiation, and death in tumors." (PMID 35563222, 2022). "In terms of individual cancer stages, the increase in SFN expression correlated with that in PC progression." (PMID 35547358, 2022). "It is also interesting to mention that stratifin (SNF), a highly conserved ubiquitously expressed protein, is associated with many different cellular processes and directly linked to cancer onset and progression." (PMID 34943605, 2021). "The clinical significance of SFN methylation identified in our analysis is also corroborated by reports in other cancer types where these epigenetic events in SFN gene were considered promising biomarkers." (PMID 34944974, 2021). "SFN (Stratifin, also called 14–3-3σ) expression is influenced by the methylation of the 5′ coding sequence resulting in gene silencing in cancer." (PMID 31029150, 2019). "Although highly expressed in normal adjacent tissues, we show an increase in SFN expression across the metaplastic-dysplastic-cancer sequence." (PMID 30404157, 2018). "Our observations suggest that this mechanism exists in multiple cell types and in tumors, and that this mechanism is worthy of additional study as a potentially important mechanism of SFN-mediated cancer prevention and therapy." (PMID 29088716, 2017). "FN in the cytoplasm of thyroid follicular cells is associated with transformation, and the co-expression of sFN, GAL3 and HBME1 is commonly observed in carcinomas, but it is restricted in benign lesions." (PMID 24696692, 2014). "Subsequently, the down-regulation of SFN gene in various human cancers was generally attributed to the hypermethylation of its CpG island." (PMID 18702824, 2008). "Both SFN and S100P have been shown to be involved in cancer progression." (PMID 39628446, 2024). "14-3-3 sigma or stratifin (SFN), found to be dually located in this work, has shown aberrant expression in various cancers, being often downregulated, but its upregulation has been associated with the development of resistance to therapeutic drugs and ECM remodeling." (PMID 39268460, 2024). "Overexpression of SFN has been reported in human malignant tumors." (PMID 37587914, 2023). "Considering the direct contribution of SFN to the cancer development, it seems that several molecular landscapes may control its downstream expression." (PMID 36160032, 2022). "SFN has been reported to play an important role in multiple kinds of tumors, including lung, breast, ovary, bile duct, and gallbladder cancers." (PMID 35936690, 2022).
cancer (continued). "The functions of SFN may vary depending on the organs and/or tissues, and several studies have shown that upregulation of SFN promotes cancer of pancreas, head and neck, lower gastrointestinal tract, lung, and gallbladder." (PMID 36160032, 2022). "Several studies support this hypothesis and have demonstrated downregulation of the SFN gene in several human cancers, including breast, ovaries, lung, liver, prostate, and oral cavity." (PMID 36160032, 2022). "In most cancers, including BC, this downregulation is known to be due to SFN gene inactivation, generally through promoter methylation; for this reason, DNA hypermethylation in the promoter of SFN has been used as a biomarker for cancer diagnosis." (PMID 36160032, 2022). "We also confirmed the upregulation of SFN in different cancers using the GENT2 tool." (PMID 35547358, 2022). "Interestingly, in the case of cancer stages, SFN expression increased proportionally with cancer stage progression." (PMID 35547358, 2022). "All these previous studies indicated that SFN plays a critical role in the migration and invasion of cancer cells, although the mechanism underlying the function of SFN in CRC invasion and migration has not been elucidated." (PMID 35936690, 2022). "Although SFN plays important role in various cancers, its role in CRC is still obscure." (PMID 35936690, 2022). "Nevertheless, SFN has been reported to be a novel biomarker in various cancers." (PMID 30926680, 2019). "We test the hypothesis that YAP1/∆Np63α signaling is targeted and suppressed by SFN as a mechanism of cancer prevention/therapy." (PMID 29088716, 2017). "As the LATS1, YAP1, ∆Np63α cascade is a potent driver of cancer stem cell survival, we decided to determine whether SFN can suppress activity in this cascade as a mechanism to suppress ECS cell survival." (PMID 29088716, 2017). "We determined whether KRT17 works by modulating the nucleocytoplasmic localization of SFN in cancer cells, as has previously been observed in mouse epidermal cells." (PMID 27512993, 2016). "The identified key proteins, such as SFN, LAMC2, and ITGB4, along with their associated pathways, could serve as potential biomarkers or therapeutic targets for overcoming resistance in this cancer type." (PMID 40959663, 2025). "The increased levels of stratifin (SFN) transcript, whose product binds to translation initiation factors and functions as a regulator of translation during mitosis, help prevent DNA errors during mitosis and could indicate cancer cell survival." (PMID 37834191, 2023). "However, SFN plays a double-edged function in human cancers, and its function may vary among organs and tissues." (PMID 35547358, 2022). "CCNA2, SFN, HMGA2, SOX2, and RBP2 have been identified as significant biomarkers for cancer diagnosis and prognosis, particularly in liver cancer." (PMID 40251374, 2025). "In analyzing the expression of stratifin (SFN), there was an overall downward trend of decreasing SFN expression as the cancer progressed." (PMID 40004538, 2025). "The expression of LPCAT1, NDRG1, G6PD, CYP7A1, SPP1, SFN, and CDCA8 was significantly higher in cancer tissues than in paraneoplastic tissues, whereas the expression of DNASE1L3 was significantly lower in cancer tissues." (PMID 37717019, 2023). "Thus, SFN could be a promising therapeutic target for several types of cancer." (PMID 35547358, 2022). "In other words, we identified higher expression of 2.366-fold of SFN (|LogFC| = 1.243), 12.915-fold of LINC01343 (|logFC| = 3.691), and 10.584-fold of CCDC18-AS1 (|logFC| = 3.397) in the cancer tissue in comparison to the control group." (PMID 36160032, 2022). "The expression levels of JUN, SFN, HSPB1, and CD47 in cancer cells and the expression levels of KLRB1, CD48, GZMK, and LY6E in CD8+ T cells were consistent with the scRNA-seq results." (PMID 33083004, 2020).
cancer (continued). "And most of the 24 DEPs (CDK1, SFN, PRKAR2B, MKI67 and MDK involved in the cell cycle; LOXL2, P4HA1, P4HA2, SPRX, DES, PRPH and CALML3 involved in construction and regulation of extracellular matrix; IL33 and EHD3 may involve in immune) were linked to cancer hallmarks." (PMID 33200655, 2020). "These experiments reveal the robustness of our results and overexpression of SFN and SPP1 in HCC promotes cancer cell proliferation." (PMID 33221766, 2020). "We also examined the expression of ESCC cancer marker genes EPCAM and SFN in two cell populations." (PMID 40244296, 2025). "Seven out of 52 genes (GSTP1, HSP90B1, HSPB1, PFN1, RAP1A, SFN, YWHAZ) were assigned to KEGG pathways in cancer, cell migration and cell cycle, and in signaling networks involved in proliferation, cellular motility, apoptosis, cell adhesion, angiogenesis and genetic integrity." (PMID 30157864, 2018). "In one study, stratifin (SFN), 14-3-3 zeta (YWHAZ), and hRNPKs (heterogeneous nuclear ribonucleoprotein K) have been identified where direct interaction between three biomarkers have been reported for their role in inflammation, signaling, proliferation, and cancer." (PMID 36776920, 2023). "However, in these studies, consideration was not given to the elevated plasma levels of sFn (which is likely to be conformationally altered) in the blood of many patients with cancer and other conditions." (PMID 16925817, 2006). "Several studies suggest that sFn may be a prognostic marker in cancer, but no clinical studies have been performed to directly associate sFn with increased metastasis." (PMID 16925817, 2006). "Therefore, for future studies, investigating the exact molecular pathways of SFN, CCDC18-AS1, and LINC01343 in cancer may shed new light on the important and emerging role and function of these factors in tumorigenesis and lead to newer approaches for both the diagnosis and treatment of BC." (PMID 36160032, 2022). "The use of fibrin blocking peptides may represent a novel class of therapeutic agents to reduce sFn mediated immunosuppression, and decrease metastasis in many cancers, while avoiding the negative bleeding problems commonly associated with anticoagulant therapies." (PMID 16925817, 2006).
adenocarcinoma (6 papers, 2008 to 2022). A common cancer characterized by the presence of malignant glandular cells. "Along with such evidence and the loss of SFN expression between metaplastic-dysplastic-adenocarcinoma tissue and normal adjacent tissues demonstrated in this study, SFN may have future promise as a prognostic biomarker in OAC." (PMID 30404157, 2018). "Although the promoter region of SFN is totally methylated in normal lung and AIS, most invasive adenocarcinomas show partial methylation, suggesting that demethylation at this site leads to overexpression of SFN." (PMID 30899432, 2019). "Recent studies have demonstrated that a highly methylated SFN promoter is found in normal lung tissue and in adenocarcinomas, however, 14-3-3σ is overexpressed in early invasive adenocarcinoma." (PMID 24923353, 2014). "Then, by staining for squamous epithelium markers (including KRT5, KRT6A, SFN, and KRT14) and columnar epithelium markers (including EPCAM and KRT8), groups 3, 7, and 10 were identified as squamous cancer cells, and groups 5, 6, and 8 were identified as adenocarcinoma cells." (PMID 36052088, 2022).
infection (3 papers, 2016 to 2019). The state of being infected such as from the introduction of a foreign agent such as serum, vaccine, antigenic substance or organism. "For example, the cell proliferation-related gene stratifin was down-regulated in our study, while it was up-regulated after the infection of C. parvum Iowa stain." (PMID 30013528, 2018). "Consistent with our qRT-PCR analysis, infection of HDFn cells with ΔNp73β in combination with KLF4 + ΔNp63α led to increased expression of KRT14, KRT5, FLG, and SFN as compared to KLF4 + ΔNp63α with control or control alone." (PMID 31216312, 2019). "Three days after infection of the HDFn cells with ΔNp73-expressing lentivirus, we harvested cells, isolated RNA, and performed qRT-PCR for keratinocyte genes that are markers of the iKC state (KRT14, KRT5, SFN, and FLG)." (PMID 31216312, 2019).
colon polyps (1 paper, 2004). "Examples include, ras-effector nore1A (RASSF1A), stratifin (14-3-3σ), p15 and p16, O6-methylguanine-DNA methyltransferase (MGMT), mismatch repair gene (hMLH1) and hyperplastic colon polyps gene (HPP1)." (PMID 15301688, 2004).
nervous system tumor (1 paper, 2020). "Among them, SFN and ELMO1 have been widely reported to associate with nervous system tumor process." (PMID 32528944, 2020).